BBC3 (BCL2 binding component 3)
Description:
Regulates ER stress-induced neuronal apoptosis (By similarity). [Isoform 3]: Does not affect cell growth.
Synonyms: PUMA; JFY1; JFY-1
Tractability: PROTAC: a small molecule that binds it is known.
Gene: Protein-coding gene on chromosome 19 (47,220,822 to 47,233,019, reverse strand). Ensembl gene ENSG00000105327.
Subcellular location: Mitochondrion
Subcellular location (Human Protein Atlas): Cytosol
Pathways (Reactome):
Gene expression (Transcription): FOXO-mediated transcription of cell death genes
Programmed Cell Death: Activation of PUMA and translocation to mitochondria; BH3-only proteins associate with and inactivate anti-apoptotic BCL-2 members
Gene Ontology:
Molecular function: ATPase binding; protein binding
Biological process: apoptotic process; execution phase of apoptosis; intrinsic apoptotic signaling pathway in response to endoplasmic reticulum stress; positive regulation of intrinsic apoptotic signaling pathway; positive regulation of release of cytochrome c from mitochondria; release of cytochrome c from mitochondria; intrinsic apoptotic signaling pathway; positive regulation of apoptotic process
Cellular component: lysosome; mitochondrion
Genetic constraint (gnomAD): Loss-of-function variants: 5 observed, 8.1 expected, observed/expected ratio (o/e) 0.62, 90% interval 0.32 to 1.29. That is too few expected variants to judge how well the gene tolerates losing a copy. Missense variants: 224 observed, 187.56 expected, observed/expected ratio (o/e) 1.19, 90% interval 1.07 to 1.33. Synonymous variants: 119 observed, 90.06 expected, observed/expected ratio (o/e) 1.32, 90% interval 1.14 to 1.54.
Homologues: Orthologues: dog BBC3 (96% identical), pig BBC3 (96% identical), rat Bbc3 (91% identical), mouse Bbc3 (91% identical), rabbit BBC3 (61% identical).
Diseases named in the same sentence as BBC3 in open-access papers:
BBC3 is named in the same sentence as 153 diseases in open-access papers, as found by Europe PMC text mining. Sharing a sentence is not in itself a finding about the gene and the disease. The quoted sentences say what the papers report.
breast cancer (43 papers, 2008 to 2025). A primary or metastatic malignant neoplasm involving the breast. "BBC3 is a pro-apoptotic gene that has been associated with breast cancer phenotype and prognosis through the rs2032809 polymorphism." (PMID 38420434, 2024). "In conclusion, BBC3 rs2032809 polymorphism was associated with breast cancer phenotype and prognosis." (PMID 34441352, 2021). "In conclusion, our results showed that BBC3 rs2032809 was associated with breast cancer phenotype and survival." (PMID 34441352, 2021). "In this study, multivariate analysis was performed to identify whether genotypes or alleles of BBC3 rs2032809 and EGFR rs2227983 polymorphisms are independent prognostic factors for OS, PFS and MFS in patients with breast cancer." (PMID 34441352, 2021). "Furthermore, identified six genes (TSPYL5, CD55, CCNE2, DCK, BBC3, and MUC1) susceptible to breast cancer were verified through the literature mining, GO analysis, and pathway functional enrichment analysis." (PMID 24073403, 2013). "In lung cancer, miR-301 has been reported to target MEOX2, while in breast cancer, it targets COL2A1, PTEN, BBC3, and FOXF2." (PMID 37509289, 2023). "Mechanism dissection indicated that the miR301a promoted breast cancer proliferation and metastasis via targeting FOXF2, BBC3, PTEN, and COL2A1, as well as down-regulated NF-kB-repressing factor and elevated NF-kB activation in human pancreatic adenocarcinoma." (PMID 25940439, 2015). "The miR-301a-3p had been reported to target MEOX2 in lung cancer, FOXF3, BBC3, PTEN and COL2A1 in breast cancer and RUNX3 in gastric cancer." (PMID 26019136, 2015). "Using netSAM, we identified six novel genes (TSPYL5, CD55, CCNE2, DCK, BBC3, and MUC1) as cancer biomarkers for predicting survival and metastasis in patients with breast cancer." (PMID 24073403, 2013). "Both its derivatives exerted pro-apoptotic action on the breast cancer MCF-7 line, where treatment with 10 nM of 4HPTTNPB resulted in a 10–20-fold increase in the induction of pro-apoptotic markers ATF3, GADD34, BBC3, and NOXA, marking its great potential as an anti-cancer treatment." (PMID 33809565, 2021). "Since statistically significant associations were estimated between heterozygous genotype of BBC3 rs2032809 and analyzed breast cancer characteristics, the analysis of allelic models was not performed." (PMID 34441352, 2021).
colorectal cancer (38 papers, 2008 to 2025). A primary or metastatic malignant neoplasm that affects the colon or rectum. "Oncogenic RAS colorectal cancer cells that are sensitive to EGFR-targeting antibodies undergo apoptosis through the p73-dependent transcriptional activation of the BH3-only protein PUMA (also known as BBC3); when these cells acquire resistance, they exhibit a reduction in PUMA expression." (PMID 35147163, 2022). "MiR-483-3p is known to target BBC3/PUMA in HCC and colorectal cancer." (PMID 35883677, 2022).
colon carcinoma (37 papers, 2007 to 2026). "In addition, BCL2 binding component 3 (BBC3/PUMA)-induced mtDNA release activates STING1-dependent necroptosis by elevating the expression of RIPK3 and MLKL in HT29 colon cancer cells and MEFs134." (PMID 34078874, 2021).
lung carcinoma (32 papers, 2010 to 2025). "It has been shown that Wnt/β-catenin signaling exhibits a regulatory activity on the expression of BBC3 in lung cancer cells." (PMID 34874225, 2021). "Decreased expression of genes, such as TNFRSF10B, MIA2, and BBC3, are answerable for the progression of various cancers, such as lung cancer, hepatocellular carcinoma, head, and neck cancer, but low expression of these genes may be responsible for the development of BRCA." (PMID 31311202, 2019). "Besides, NT157 decreased expression of oncogenes BCL2, CCND1, MYB, and MYC and increased genes related to cellular stress and apoptosis, JUN, BBC3, CDKN1A, CDKN1B, FOS, and EGR1 (p < 0.05), favoring a tumor-suppressive cell signaling network in the context of lung cancer." (PMID 36224313, 2022).
melanoma (29 papers, 2006 to 2025). A malignant, usually aggressive tumor composed of atypical, neoplastic melanocytes. "We additionally confirmed the expression with mRNA levels of key genes after treatment with lj-1-59 in melanoma cells, which indicated that P21, BBC3, SESN2 and GADD45A expression were significantly upregulated, while MCM2, MCM3, MCM4, MCM7 and PKMYT1 were significantly downregulated." (PMID 32021565, 2020).
ovarian carcinoma (22 papers, 2012 to 2025). A malignant neoplasm originating from the surface ovarian epithelium. "Among these genes, BBC3 has been reported to be associated with cisplatin resistance in ovarian cancer, and has been proposed as a chemosensitizer in platinum compounds-based ovarian cancer therapy." (PMID 34858477, 2021). "Moreover, SOX-2 was also found to induce resistance by increasing anti-apoptotic proteins like Bcl-2 and decreasing pro-apoptotic proteins like PUMA/BBC3 in ovarian cancer cells." (PMID 38864530, 2024).
lymphoma (19 papers, 2015 to 2025). A malignant (clonal) proliferation of B- lymphocytes or T- lymphocytes which involves the lymph nodes, bone marrow and/or extranodal sites. "Eμ-Myc lymphoma cells treated with M-100 de-repressed Bbc3 as well as Pmaip1 and repressed Bcl2 expression." (PMID 36068335, 2022).
prostate carcinoma (19 papers, 2007 to 2025). A carcinoma that arises from epithelial cells of the prostate gland. "Several additional tumor suppressors were similarly affected by promoter-closing variants, including BBC3 (PUMA), a pro-apoptotic gene that suppresses prostate cancer cell growth, and known tumor suppressors, ATL3 and ING5." (PMID 41468516, 2025).
glioblastoma (18 papers, 2010 to 2025). The most malignant astrocytic tumor (WHO grade IV). "As observed in other cell types, overexpression of SNAI2/Slug in U251 glioblastoma cells decreased BBC3/PUMA mRNA expression and increased expression of angiogenic factors such as VEGF, IL8 and several extracellular matrix proteins by more than 1.5 fold." (PMID 20565806, 2010). "Elevated levels of Mir221 and Mir222 in glioblastoma promote cell survival, while reducing the levels of these miRNAs leads to increased apoptosis through the upregulation of BBC3/PUMA." (PMID 39245438, 2025).
gastric cancer (12 papers, 2012 to 2025). A primary or metastatic malignant neoplasm involving the stomach. "The seven RNAs upregulated in gastric cancer were CLDN18, EPCAM, REG4, BBC3, OLFM4, PPARG, and CDH17, while the two downregulated genes were IFITM1 and HIF1A." (PMID 22929309, 2012).
osteosarcoma (12 papers, 2009 to 2025). A usually aggressive malignant bone-forming mesenchymal neoplasm, predominantly affecting adolescents and young adults. "p21 was found to be frequently down‐regulated in osteosarcoma, and it exhibited inhibitory roles in the growth of this cancer.28, 29puma, also known as BBC3, is a pro‐apoptotic gene." (PMID 31218831, 2019). "Collectively, our data indicate that bufalin inhibits cell proliferation and induces mitochondria-dependent apoptosis in osteosarcoma cells through downregulating miR-221 and triggering BBC3 expression." (PMID 28074104, 2016). "BBC3 (Bcl2 binding component 3) inhibited the progression of osteosarcoma." (PMID 36903477, 2023). "However, BBC3 is directly targeted by miR-221 in osteosarcoma cells." (PMID 36903477, 2023).
cervical cancer (11 papers, 2011 to 2023). A primary or metastatic malignant neoplasm involving the cervix. "It implies that ERs-related genes (ATF4 and DDIT3) and downstream apoptosis genes (JUN, FOS, BBC3, and PMAIP1) are the potential targets of 20(S)-GRh2 and might be interacting with each other to be involved in the apoptosis induction in cervical cancer cells." (PMID 36431966, 2022). "Combined protein–protein interaction network, hub gene screening, and qPCR validation data showed that ERs-related genes (ATF4 and DDIT3) and the downstream apoptotic genes (JUN, FOS, BBC3, and PMAIP1) were potential novel targets of 20(S)-GRh2-inducing cervical cancer cell apoptosis." (PMID 36431966, 2022).
pancreatic cancer (11 papers, 2012 to 2026). "The PUMA gene, also named BBC3, has been reported in previous studies to be associated with pancreatic cancer." (PMID 32943991, 2020). "In fact, the analyzed TCGA data on breast, lung, and pancreatic cancer report that HOPS/TMUB1 expression positively correlates with the three genes of the apoptotic response: BAX, BBC3, and NOXA1." (PMID 38731819, 2024).
Burkitt lymphoma (8 papers, 2015 to 2024). A rare form of malignant mature B-cell non-Hodgkin lymphoma. "Moreover, ectopic expression of EAF2 also induced apoptosis in a human Burkitt's lymphoma line Daudi, which again was accompanied by decreased BCL-2 protein expression and increased BBC3 transcript level." (PMID 26935903, 2016).
Sepsis (6 papers, 2010 to 2026). Sepsis is defined as life-threatening organ dysfunction caused by a dysregulated host response to infection. "Downregulation of BCL2 and BBC3 gene expression was observed in sepsis patients (p < 0.05), but not in uncomplicated infection, potentially contributing to differences in the severity of metabolic impairment." (PMID 41704334, 2026). "Moreover, transcript levels of the pro-apoptotic genes BAK1, CYCS, BBC3, CASP7, and CASP8 were upregulated in the COVID-19 cohort, whereas those of anti-apoptotic genes, such as BCL2L11 and BCL2L1, were upregulated in the sepsis cohort." (PMID 36443881, 2022).
Huntington disease (4 papers, 2017 to 2023). Huntington disease (HD) is a rare neurodegenerative disorder of the central nervous system characterized by unwanted choreatic movements, behavioral and psychiatric disturbances and dementia. "We also found many differentially expressed genes related to the Huntington disease (HD) pathway in both areas of the MPS II mouse model; among these, Bbc3, Bdnf, Crebbp, Dctn1, Dlg4, Gpx1, Grin1, Grin2b, Itpr1, and Pparg are up-regulated, while Dnaic2, Dnali1, Hap1, and Vdac2 are down-regulated." (PMID 28513549, 2017).
acute lymphoblastic leukemia (3 papers, 2017 to 2021). Leukemia with an acute onset, characterized by the presence of lymphoblasts in the bone marrow and the peripheral blood.
silicosis (3 papers, 2015 to 2021). Silicosis is a respiratory disease caused by breathing in (inhaling) silica dust. "Collectively, these results suggest that increased BBC3 expression in macrophages is causally linked to fibroblast activation and migration during silicosis." (PMID 28277537, 2017). "To further determine whether the autophagic protein regulation of BBC3 was associated with human silicosis, we examined the expression of BBC3 and autophagy proteins in macrophages from the BALF of normal subjects and silicosis patients." (PMID 28277537, 2017). "Therefore, we postulated that BBC3 may participate in the development of silicosis, and we conducted experiments to assess whether BBC3 changes were associated with the activation and apoptosis of macrophages exposed to SiO2." (PMID 28277537, 2017). "Collectively, these results suggest that BBC3 contributes to the regulation of autophagy protein expression during silicosis." (PMID 28277537, 2017). "In the mouse model of silicosis, Bbc3 knockout mice clearly exhibited decreased levels of autophagy and fibrosis progression." (PMID 28277537, 2017). "Meanwhile, is the knockdown of BBC3 or NALP3 expected to be an intervention target for silicosis?" (PMID 33466366, 2021). "The results indicate that BBC3 is involved in the pathological progress of silicosis." (PMID 28277537, 2017). "As an inducer of apoptosis, the role of BBC3/PUMA (BCL2-binding component 3) in macrophages during silicosis remains unknown." (PMID 28277537, 2017). "In addition, compared with healthy people, silicosis patients showed significantly increased expression levels of BBC3 and autophagic proteins in BALF macrophages." (PMID 28277537, 2017). "Subsequently, our results demonstrated that treating the macrophages with Bbc3-specific siRNA remarkably inhibited cell activation and apoptosis, suggesting that silicosis resulting from macrophage activation and apoptosis may depend on the upregulation of BBC3." (PMID 28277537, 2017). "BBC3 has been speculated to promote the development of silicosis through inducing autophagy." (PMID 28277537, 2017).
cardiomyopathy (2 papers, 2021 to 2022). A disease of the heart muscle or myocardium proper. "Those authors identified genes implicated in cardiac calcium homeostasis (PDE3B), oxidative stress response (FDXR and SPATA18), and the etiology of cardiomyopathy (SGCD, BBC3 and GDF15)." (PMID 33820914, 2021).
pulmonary fibrosis (2 papers, 2017 to 2024). Chronic progressive interstitial lung disorder characterized by the replacement of the lung tissue by connective tissue, leading to progressive dyspnea, respiratory failure, or right heart failure. "In vitro studies using human lung fibroblasts have confirmed that circ_0001861 modulates the miR-296-5p/BBC3 (BCL2 binding component 3) axis to mitigate pulmonary fibrosis." (PMID 39479511, 2024). "And BBC3 mediated the fibroblast activation and migration through inducing macrophage autophagy and apoptosis, suggesting an important role of BBC3 in macrophages in SiO2-induced pulmonary fibrosis." (PMID 28277537, 2017). "Furthermore, Sirius Red staining results also indicated that Bbc3 knockout significantly alleviated pulmonary fibrosis compared with WT group treated with SiO2." (PMID 28277537, 2017).
anaplastic thyroid cancer (1 paper, 2023). "These include the BH3‐containing protein BBC3/PUMA, whose downregulation prevents apoptosis in cell lines of various origins, and PARD3, whose targeting increases TGF‐β1‐induced invasion in anaplastic thyroid cancer." (PMID 36862005, 2023).
cognitive deficits (1 paper, 2018).
Ewing sarcoma (1 paper, 2023). A small round cell tumor that lacks morphologic, immunohistochemical, and electron microscopic evidence of neuroectodermal differentiation.